MYD88 (MYD88 innate immune signal transduction adaptor)
Diseases named in the same sentence as MYD88 in open-access papers (continued):
Sharing a sentence is not in itself a finding about the gene and the disease.
bacterial infection (continued). "Moreover, MyD88-deficient mice have impaired monopoiesis during bacterial infection resulting in significant reduction in blood, splenic and bone marrow progenitors of inflammatory monocytes." (PMID 21235801, 2011). "Although corals are thought to only possess an innate immune system, the presence of the MyD88-dependent Toll-like receptor signaling pathway is an example of an adaptive-like immune response system that may help corals mitigate bacterial infections associated with severe sedimentation." (PMID 38919851, 2024). "However, because IL-18 is also produced from macrophages by LPS stimulation and is also an activator of MyD88 signaling, it may also influence the development of disease associated with bacterial infection." (PMID 31507610, 2019). "MYD88-dependent pathways are involved in various immune responses, including those against viral and bacterial infections." (PMID 40870825, 2025). "Bacterial infection and LPS treatments have been reported to inhibit osteogenic differentiation of BMSCs via MyD88/NF-κB signaling." (PMID 40791819, 2025). "Oxidative stress, TLR4/Myd88/NF-κB related inflammatory signaling, and apoptosis are important body responses in response to bacterial infection." (PMID 40239311, 2025). "This indicates that DDX5 was recruited to Hrd1 in an MyD88-dependent manner during bacterial infection." (PMID 38182816, 2024). "We further show that OTUD4 negatively regulates the expression of AMPs in IECs after DSS treatment or bacterial infection in a MyD88-dependent manner." (PMID 37193092, 2023). "This phenotype was also observed in MyD88- and IRAK-4–deficient patients with pyogenic bacterial infections." (PMID 36880831, 2023). "It has been demonstrated that TLR-mediated MyD88-dependent signaling promotes the expression of AMPs and regulates bacterial infections and inflammation in the gut." (PMID 37193092, 2023). "Activation of the downstream NF-κb pathway via MyD88 produces IFNs and pro-inflammatory or anti-inflammatory cytokines to antagonize bacterial infections." (PMID 37256135, 2023). "Here in this study, we have demonstrated that OTUD4 inhibits the expression of AMPs in Paneth cells and supports intestinal inflammation and bacterial infection through deubiquitinating MyD88." (PMID 37193092, 2023). "MyD88 is important for host defense against several bacterial infections, including S. pneumoniae, E. coli, K. pneumoniae, H. influenzae, P. aeruginosa, S. aureus, and L. pneumophila." (PMID 37662905, 2023). "Our results showed that the expression levels of TLR4, TLR5, and MyD88 mRNA in the bladder epithelial cells were upregulated in response to the bacterial infection." (PMID 36506014, 2022). "While the regulation of On-VIP on the MyD88 pathway was specific to tissues after bacterial infection, thus promoting its expression in the intestine and spleen and inhibiting its expression in the liver and brain." (PMID 36499231, 2022). "The most represented family is miRNA‐148 with 219 copies, which is known to act as a negative regulator of MyD88‐dependent NF‐κB signaling in the teleost fish and inhibited in the herbivorous carp Ctenopharyngodon idella, in response to bacterial infection." (PMID 36426129, 2022). "In the immune system response to bacterial infection, an important role is played by the MyD88-dependent signaling pathway, which is initiated by binding of the adaptor protein MyD88 to the TIR domain of the toll-like receptor." (PMID 35095609, 2021). "Inherited defects in both MyD88 and IRAK4 have been described, with loss of either factor leading to a similar phenotype involving a predilection for severe bacterial infections in early childhood." (PMID 34199501, 2021). "Deficiencies in both MyD88 and IRAK-4 are characterized by recurrent, severe pyogenic bacterial infections involving Streptococcus pneumoniae, Staphylococcus aureus and Pseudomonas aeruginosa." (PMID 34199501, 2021).
bacterial infection (continued). "IEI resulting from inherited defects in MyD88 were initially described in nine children from five unrelated kindreds with recurrent, severe pyogenic bacterial infections." (PMID 34199501, 2021). "A growing amount of literature has demonstrated the key role of TLR/MyD88 signaling in bacterial infections." (PMID 32182946, 2020). "Because MyD88 has been shown to be required for interferon signalling following bacterial infection in Brucella abortus, this would be consistent with the present findings." (PMID 32678312, 2020). "Myeloid differentiation primary response 88 (MyD88) is an intracellular adapter protein that receives signals by all toll-like receptors (TLRs) and is involved in the immune response to bacterial infection." (PMID 33260434, 2020). "It is well-known that TLR4/MYD88 is responsible for the upregulation of NF-κB signaling in response to bacterial infection in various conditions." (PMID 32110933, 2020). "Specifically, TLR9 constitutively associates with Cav-1 and facilitates MyD88-mediated TRAF3 and IRF3 signal transduction, providing the observed InP effect in fatal doses of bacterial infection." (PMID 31534550, 2019). "We described for the first time a female patient with the simultaneous presence of two homozygous mutations in MYD88 and CARD9 genes presenting with pyogenic bacterial infections, elevated IgE, and persistent EBV viremia." (PMID 30837984, 2019). "Unexpectedly, we found that myd88, along with several other genes known to be regulated in a Myd88 dependent manner during bacterial infection, is among the down regulated genes in conventionalized larvae." (PMID 30291253, 2018). "The induction of type I interferon in macrophages and dendritic cells in response to bacterial infections has been canonically traced to MyD88-independent signaling via TLR4 responses to LPS." (PMID 28453531, 2017). "miR-146a is strongly up-regulated upon TLR stimulation and serves as a negative regulator of the MYD88-NF-κB signaling pathway after bacterial infection." (PMID 26689540, 2015). "Toll-like receptors (TLR) and the downstream adaptor protein MyD88 are considered crucial for protective immunity during bacterial infections." (PMID 25700108, 2015). "MyD88 has an important role in early recruitment of inflammatory cells and in the control of bacterial infection." (PMID 24830455, 2014). "Based on microarray analysis and Taqman miRNA assays we conclude that members of the miR-146 family, which is highly conserved between fish and human, are induced by bacterial infection in zebrafish in a MyD88 and Traf6 dependent manner." (PMID 24112639, 2013). "Mutations in IRAK 4 and MYD88 in humans impair some of the TLR pathways and are associated with predisposition to pyogenic bacterial infections." (PMID 22723961, 2012). "According to the mammalian model, NF-kB was assumed to participate in signal transduction of the TLR (MyD88- dependent) pathway besides cytokine release in response to bacterial infection." (PMID 21637513, 2009). "Its regulatory effects on the MyD88/NF-κB signaling pathway, as well as its involvement in inflammasome and pyroptosis regulation, highlight its potential function in maintaining immune homeostasis during bacterial infections." (PMID 41017465, 2025). "MyD88 is a key component of the Toll signaling pathway, which is predominantly induced by Gram-positive bacteria and fungi in Drosophila flies, but the importance of Toll activation in controlling bacterial infections in ticks is poorly understood." (PMID 39450335, 2024). "However, Myd88−/− mice exhibit changes in the functionality of the intestinal barrier and are unable to control bacterial infection." (PMID 37234258, 2023). "Since the discovery of MyD88, a considerable progress has been made on the understanding of MyD88-linked antiviral type I IFN response and other pro-inflammatory cytokine responses with many viral and bacterial infections including its spatiotemporal regulation and function." (PMID 33834387, 2021).
bacterial infection (continued). "IRAK-4 (MIM 607676) and MyD88 (MIM 612260) deficiencies, which are phenocopies in term of clinical and immunological abnormalities, are characterized by a selective predisposition to pyogenic bacterial infections." (PMID 32625202, 2020). "Bacterial infections involving the orofacial region such as maxillary sinusitis, necrotizing palate infection, cellulitis, and periodontal diseases have been reported in some patients with IRAK-4 and MyD88 deficiencies." (PMID 32625202, 2020). "However, in contrast to the two pyogenic bacterial disease-associated point mutants, L93P within the DD and R196C within the TIR domain, the L252P mutant dramatically enhances MyD88 self-association." (PMID 30583727, 2018). "Moreover, it also defends against bacterial infection by mediating MyD88-independent activation of NF-kB and production of inflammatory mediators." (PMID 29799862, 2018). "Thus, our findings support the established model for a dominant role of the MyD88-dependent pathway in response to bacterial infection." (PMID 29799862, 2018). "Interestingly, Myd88 has been shown to participate in immune activation after bacterial infection of the CNS in mice." (PMID 28871168, 2017). "This suggests that MyD88 may have a role during intracellular bacterial infection signalling from endosomal compartments leading to PKR activation." (PMID 27021640, 2016). "The results from this current study provide evidence to demonstrate that H. polygyrus infection-induced development of alternatively activated macrophages is MyD88 independent, which may contribute to impaired control of bacterial infection." (PMID 25010669, 2014). "Together, these results indicate that RV-induced reductions in IRAK-1 may attenuate chemokine production in response to secondary bacterial infection via desensitization of MyD88-dependent TLR signaling." (PMID 23055935, 2012). "Most importantly, expression of these miRNAs was augmented during the vacuolar host response, in a MyD88-dependent manner, and differentially regulated by NF-κB p65, suggesting that they are part of the early innate immune response of macrophages to bacterial infection." (PMID 22114673, 2011). "Moreover, it remains unknown whether and how the MYD88-mediated host defense system of osteocytes triggered by bacterial infection impacts the skeleton." (PMID 36333322, 2022). "For example, miR-203 could target myd88 in macrophages against LPS or bacterial infection." (PMID 26274503, 2015). "Moreover, the increase in bacterial infection and disease severity were found to be correlated with a significant downregulation of antimicrobial peptide expression in the intestinal tissue in co-infected MyD88 knockout mice." (PMID 25010669, 2014). "Upon bacterial infection, DDX5 is recruited to Hrd1 at the endoplasmic reticulum in an MyD88-dependent manner and is degraded by the ubiquitin-proteasome pathway." (PMID 38182816, 2024). "Numerous studies have investigated the roles of adaptor proteins involved in TLR pathways, including the MyD88-dependent cascade (MyD88 and TIRAP) and the MyD88-independent cascade (TRIF and TRAM) in bacterial infections." (PMID 37662905, 2023). "The studies herein have identified the downstream ISGs TNRFSF10A, PML, MYD88, EHD4, and HK2 that potentiate secondary bacterial infection." (PMID 37939149, 2023). "TIRAP, also known as MYD88 adapter-like (Mal), is an important link between MYD88 and the receptor complex formed by TLR2 and TLR4 activation following bacterial infection." (PMID 35140801, 2022).
bacterial infection (continued). "For example, B. melitensis TcpB, described as a molecular mimicry of TIRAP, can bind with MyD88 and TIRAP via TIR–TIR interaction to promote the ubiquitin-mediated degradation of TIRAP during bacterial infection." (PMID 34305858, 2021). "Future studies will need to determine if S1PR2 can co-localize with TLR4, MyD88, RANK, TRAF6, MAPKs, PI3K, Src, and integrins in lipid rafts in response to bacterial infection or RANKL stimulation." (PMID 30609675, 2019). "For example, MyD88 adaptor-like (Mal) acts to bridge MyD88 to TLR4 or TLR2 complex and is capable of mediating NF-kB activation in response to bacterial infection." (PMID 24278275, 2013). "Regarding the downstream of MyD88/TIRAP pathways, we subsequently investigated two structural classes of NF‐κB protein expression, which played a key role in regulating the immune response to bacterial infection." (PMID 33463070, 2021). "In addition, it was found that the expression of MyD88, TRAF6 and TAK1 molecules are involved in the mechanism of TLR4 in human endometrial endothelial cell responses to bacterial infection." (PMID 25371751, 2014). "Interestingly, studies in transgenic zebrafish have revealed that MyD88 is able to trigger TLR-mediated immunity, contributing to essential responses to wounding and bacterial infection." (PMID 24124487, 2013). "An obvious limitation of the developed MyD88 KO mouse model of catarrhal pertussis consists in the artificial reduction of B. pertussis-host interaction complexity through ablation of the key TLR signaling pathways that activate innate and adaptive immune responses to bacterial infection." (PMID 35395059, 2022). "MyD88-dependent regulation of miR-125a-3p may prove to be a mechanism to control antigen stability and epitope generation via NTAN1 and the N-end rule pathway upon bacterial infection." (PMID 28445535, 2017). "However, the relevance of TLRs for NK cell activation during bacterial infections is unclear as NK cell-autonomous MyD88-dependent TLR signaling does not contribute to NK cell stimulation." (PMID 29112952, 2017). "Consequently, MyD88 mediated signaling could be central for hepcidin induction upon bacterial infection in vivo and is not properly targeted by the inhibitors used." (PMID 34368018, 2021). "To our surprise, we found that CCN1 can by itself induce inflammatory responses in the absence of bacterial infection through physical interaction with TLR2 and TLR4 to activate MyD88-dependent signaling." (PMID 32144270, 2020). "Since the potential role of other PRRs, including TLRs, for the induction of inflammatory cytokines during the bacterial infection has been reported, we examined the expression of type I IFN and TNF-α in professional phagocytic BMDMs lacking MyD88 or TRIF, the essential adaptors for TLR signaling." (PMID 30233599, 2018).
inflammation (45 papers, 2008 to 2026). Aberrant reaction of the microcirculation characterized by movement of fluid and leukocytes from the blood into extravascular tissues. "Excessive alcohol consumption induces the release of proinflammatory cytokines by activating the TLR4/MyD88/NF-κB signaling pathway that causes liver inflammation." (PMID 36788475, 2023). "TLR4 activation leads to increased expression of inflammatory genes such as NF-κB, Myd88, and CD14, resulting in the production of inflammatory cytokines (IL-1β, IL-6, TNF-α), which cause liver inflammation and damage." (PMID 40362886, 2025). "The activation of NLRP3 inflammasome and MyD88 myddosome increases the secretion of pro-inflammatory cytokines, such as IL-β, thereby contributing to chemotherapy-induced cardiac inflammation and fibrosis." (PMID 38700665, 2024). "Previous studies have demonstrated the important role of the TLR4/MyD88/NF-κB pathway in liver inflammation." (PMID 38790731, 2024). "Previous research suggested that synovial inflammation can affect the cartilage innate immune system through TLR4/MyD88 signalling pathway, induce cartilage inflammation and degeneration and then aggravate the OA process." (PMID 34964259, 2022). "Lycopene alleviated HDF-induced renal inflammation by inhibiting the TLR4/MyD88 inflammatory pathway by blocking inflammation in mice kidneys, including NF-kB, TNF-a, and IL-6." (PMID 36230117, 2022). "These suggested that chronic cold stress activated the TLR4/MyD88 pathway to induce lung inflammation." (PMID 36142633, 2022). "The myD88-dependent pathway is important in pulmonary inflammation and is required for the infiltration of neutrophils." (PMID 34366849, 2021). "In vivo, SAMPs induced MyD88-dependent lung inflammation characterized by accumulation of proinflammatory and cytotoxic mediators and immune cell infiltration, as well as splenic DC phenotypical maturation." (PMID 34375313, 2021). "Our current study indicated that DOX induced the increased formation of the TLR2/MyD88 complex, which leads to the activation of the NF-κB pathway and stimulates the expression of cardiac inflammation and fibrosis." (PMID 33928085, 2021). "A recent study showed that Toll-like receptor 4/MyD88 pathway activation was one of two major immune responses in acute lung inflammation in mice after intratracheally instillation of PM2.5." (PMID 33194559, 2020). "BML-111 and anti-IL-1β antibody restrains the OVA-induced airway inflammation via downregulation of the TLR2/MyD88/NF-κB pathway." (PMID 25760938, 2015). "Tlr4-/- mice displayed an intermediate phenotype, suggesting that both TLR4-dependent and –independent pathways that utilize the MyD88 adapter protein contribute to acute lung inflammation and injury following ischemia and reperfusion." (PMID 24146959, 2013). "We conclude that MyD88-dependent signaling through multiple receptors is important in the pathogenesis of acute lung inflammation and injury following ischemia and reperfusion." (PMID 24146959, 2013). "TLR/MyD88 signalling activation has been commonly observed in Ang II‐induced cardiac inflammation." (PMID 40682481, 2025). "In this study, we first showed that PM2.5-induced inflammatory cell infiltration in the lung tissue is related to the increased expression levels of MyD88 protein, thus suggesting that MyD88 may regulate PM2.5-induced acute airway inflammation." (PMID 35795853, 2022). "The present study indicated that the inhibitory effects of anti-IL-1β antibody on OVA-induced airway inflammation may be mediated by the inhibitory role of anti-IL-1β antibody on the TLR2/MyD88/NF-κB pathway." (PMID 25760938, 2015). "We hypothesized that lung inflammation and vascular barrier dysfunction following lung ischemia-reperfusion is mediated through MyD88-dependent recognition of endogenous ligands." (PMID 24146959, 2013). "Thus, hfPMSCs may attenuate BLM-induced lung inflammation and fibrosis, partly through the MyD88-mediated attenuation of inflammation in mice." (PMID 36834561, 2023).